INS (insulin)
Diseases named in the same sentence as INS in open-access papers (continued):
Sharing a sentence is not in itself a finding about the gene and the disease.
type 1 diabetes (continued). "The concept that HLA molecules play an important role in guiding antigen-specific autoimmunity in type 1 diabetes is not new as previous studies demonstrate that the first appearance of either GAD or insulin autoantibodies was associated with HLA-DR3-DQ2 and DR4-DQ8, respectively." (PMID 32754804, 2020). "Type 1 diabetes mellitus (T1DM) is an autoimmune disease in which pancreatic β cells are destroyed by autoreactive T cells, resulting in lifelong insulin dependency." (PMID 33034128, 2020). "In patients with newly diagnosed type 1 diabetes, the endogenous leptin levels are generally decreased, and they are also very low in patients with diabetic ketoacidosis but rise again after initiation of insulin therapy, possibly because of a direct effect of insulin on leptin release." (PMID 31743040, 2020). "Therefore, the objective of this study was to develop an algorithm, that is, a personalized health model that can automatically detect the incidence of infection in people with type 1 diabetes using blood glucose levels and insulin-to-carbohydrate ratio as input variables." (PMID 32784179, 2020). "Additionally, many autoantigens in type 1 diabetes originate from the insulin granule, which may require enhanced immunomodulatory functions under high-glucose conditions." (PMID 32792475, 2020). "Type 1 diabetes mellitus (T1DM) is a chronic disease characterized by immune-mediated beta-cell destruction requiring lifelong insulin therapy." (PMID 32053613, 2020). "Subcutaneous (sc) basal and prandial insulin administration is a key component of multiple daily injection (MDI) therapy in patients with type 1 diabetes (T1D) and with insulin-dependent type 2 diabetes (T2D)." (PMID 32125178, 2020). "People with type 1 diabetes (T1D) are required to administer exogenous insulin via multiple daily insulin (MDI) regimen or automated pump therapy." (PMID 33193089, 2020). "Manufacturing and production of insulin (traditional insulins and analog insulins) and insulin pumps, despite being inexpensive in producing countries, is shipped to low- and middle-income countries for high prices which is a major problem for the managing of type 1 diabetes patients." (PMID 32296622, 2020). "Type 1 diabetes mellitus (T1DM) is an autoimmune disorder in which the immune system destroys insulin-producing beta cells, leading to elevated blood glucose levels." (PMID 32503335, 2020). "Type 1 diabetes, also referred to as “autoimmune diabetes”, is a chronic autoimmune disease characterized by spontaneous, aberrant T and B cell immune responses against pancreatic beta cells, whose physiological function is to secrete insulin to regulate glucose metabolism." (PMID 32549343, 2020). "Notably, insulin deficiency may be the core factor contributing to T1DM-induced DCM, since insulin treatment can quickly reverse the phenotypes and the abnormalities observed in the hearts of patients with type 1 diabetes." (PMID 32256959, 2020). "Youth with type 1 diabetes (T1D) have several options for their insulin delivery method including standard therapy or an intensified regimen with multiple daily injections or insulin pump therapy." (PMID 31900152, 2020). "Thus, type 1 diabetes is also known as insulin-dependent DM." (PMID 32641151, 2020). "Besides genetics, the development of type 1 diabetes mellitus is also attributed to SLC30A8 polymorphism, overexpression of ZnT8, viral infections (Coxsackie, rhinovirus, and adenovirus) and ZnT8 exposure during insulin release." (PMID 32292675, 2020). "Of note, the streptozotocin-induced type 1 diabetes model is characterized by more complex metabolic changes, including drastic decrease of insulin levels and alteration of leptin signalling, which may explain the differences between our in vivo and in vitro models." (PMID 32974347, 2020).
type 1 diabetes (continued). "Type 1 Diabetes (T1D) is a chronic disease that requires a daily self-care and the adoption of specific behaviors to appropriately manage the disease: it demands frequent glycemic monitoring, insulin dose adjustment and vigilance due to risks of hypoglycemia and hyperglycemia." (PMID 32211074, 2020). "Although islet transplantation can be an effective therapy for type 1 diabetes, a severe shortage of donors, immunosuppression, and patient specificity issues have led researchers to seek alternative approaches to overcome life-long exogenous insulin dependency and transplantation complications." (PMID 32235681, 2020). "Finally, people with Type 1 Diabetes with too little insulin in their system may experience an increase in BGL (which was already high before the exercise) when they indulge in physical exercise." (PMID 32155149, 2020). "In addition to the inability to lower insulin secretion into the portal circulation at exercise onset, glucagon fails to rise normally during prolonged exercise in type 1 diabetes, predisposing athletes to developing hypoglycaemia during some activities." (PMID 32533229, 2020). "In contrast to the lack of “honeymoon period” in AAD, it therefore seems that a proportion of patients do have a durable low-level adrenal steroidogenesis, which may be considered parallel to persistent C-peptide positivity indicating low-level insulin secretion in patients with type 1 diabetes." (PMID 32300791, 2020). "People with type 1 diabetes have absolute insulin deficiency, and while people with obesity and type 1 diabetes may achieve improved glycaemic control following bariatric surgery, they will not be expected to achieve glycaemic remission and insulin withdrawal." (PMID 32743907, 2020). "Type 1 diabetes (T1D) is a chronic health condition resulting from pancreatic beta cell dysfunction and insulin depletion." (PMID 32517068, 2020). "Therapeutic approaches to combat type 1 diabetes (T1D) include donor pancreas transplantation, exogenous insulin administration and immunosuppressive therapies." (PMID 32152396, 2020). "Interestingly, previous studies have shown that induced beta cell rest may be used to preserve residual insulin secretion in patients newly diagnosed with type 1 diabetes." (PMID 32618430, 2020). "However, no studies have been conducted to determine whether subcutaneous insulin therapy per se is an independent contributing factor for the reduced pulmonary function described in type 1 diabetes." (PMID 32344939, 2020). "Type 1 diabetes (T1D) is a multifactorial autoimmune disease characterized by T cell-mediated destruction of insulin producing β cells of the pancreas." (PMID 32204344, 2020). "Also, tissue-specific genes with protein products entering the bloodstream may find applications as biomarkers (KLK3 in prostate cancer) or replacement therapies (e.g., insulin in type 1 diabetes)." (PMID 31076736, 2019). "Type 1 diabetes mellitus (T1DM) is a serious chronic disease characterized by the inability of the pancreas to secrete insulin and onset is rapid occurring over a number of weeks." (PMID 30565796, 2019). "Type 1 diabetes (T1D) is characterized by the immune-mediated destruction of the pancreatic β cells, resulting in the lifelong need for exogenous insulin treatment." (PMID 31775218, 2019). "Fluctuating insulin levels resulting from increases in circulating glucose represent a normal aspect of our metabolic regulation; however, most previous studies have utilized all-or-none insulin replacement strategies similar to the pathologies seen in type 1 diabetes." (PMID 30862903, 2019). "Type 1 diabetes (T1D) is an autoimmune disease resulting from the destruction of insulin-secreting islet β cells by autoreactive T cells." (PMID 31387620, 2019). "However, people with type 1 diabetes are born to have a mutation where they are not able to produce adequate amounts of insulin." (PMID 31485387, 2019).
type 1 diabetes (continued). "Some contributions concentrated more on the insulin secretion mechanisms, others more with short-term modelling of perturbation experiments, and some publications describe more complex models, from multi-organ models to maximal models for in-silico Type 1 diabetes virtual patient simulation." (PMID 30768604, 2019). "Type 1 diabetes (T1D) is a lifelong condition characterized by the destruction of the pancreatic beta cells responsible for insulin production." (PMID 31323886, 2019). "Additionally, fuel oxidation in the mitochondria produces reactive oxygen species (ROS), which may contribute to the long-term deterioration of insulin secretion and could be involved in the autoimmune destruction of type 1 diabetes." (PMID 31781665, 2019). "In the daily management of type 1 diabetes (T1D), determining the correct insulin dose to be injected at meal-time is fundamental to achieve optimal glycemic control." (PMID 31323886, 2019). "The type 1 diabetes is caused by an auto-immune reaction, in which the patient body defense system attacks the insulin producing beta cells in the pancreas and hence the body can no longer produce the insulin it needs." (PMID 30630432, 2019). "Mainly individuals with type 1 diabetes reported using food databases (Adit, aged 22 years; Cheng, aged 23 years; Pang, aged 19 years), likely because of type 1 patients’ greater need for food-content information to accurately adjust their insulin with food intake." (PMID 30924786, 2019). "However, type 1 diabetes is very different from haemophilia, and even if insulin can be expressed successfully there are additional challenges that need to be overcome before insulin gene therapy could be considered in people with type 1 diabetes." (PMID 30514969, 2019). "Type 1 diabetes mellitus (T1DM) is an autoimmune reaction against the insulin-producing β-cells, which leads to cytokine-mediated β-cell loss." (PMID 30679186, 2019). "Type 1 diabetes (T1D) is an autoimmune disease characterized by the progressive destruction of the insulin-producing β-cells in the pancreatic islets of Langerhans by autoreactive T cells." (PMID 31156627, 2019). "Type 1 diabetes mellitus (T1DM) is an autoimmune metabolic disorder due to the destruction of insulin-producing pancreatic β-cells by a specific auto-antibody that, over the years, strongly compromises patients’ life quality." (PMID 31771129, 2019). "Indeed, later studies targeting the B:9–23 insulin epitope presented on I-Ag7 showed that the TCR-like mIgG1 mAb287 delayed disease onset in diabetic NOD mice as an experimental model for type 1 diabetes (T1D) when administered at both early or late stages of disease." (PMID 31544838, 2019). "In addition, it is also possible that peripheral tolerance might be involved in the pathogenesis of insulin‐triggered type 1 diabetes." (PMID 30970177, 2019). "The strength of our findings is in demonstrating the glycaemic control benefit from use of flash sensor technology by MDI therapy users with type 1 diabetes, indicating the improvement is associated with the information provided by the technology not a specific insulin treatment modality." (PMID 29273897, 2018). "Islet transplantation is a therapeutic procedure that can restore endogenous insulin production and maintain euglycemia for a sustained period in patients with difficult to control type 1 diabetes mellitus (T1DM)." (PMID 30419033, 2018). "Normal C-peptide, however, needn't necessarily exclude type 1 diabetes since endogenous insulin production in type 1 diabetes may be detectable for a variable length of time, including honeymoon period, particularly in LADA (late-onset autoimmune diabetes in adults)." (PMID 30013516, 2018). "Type 1 diabetes (T1D) is an autoimmune disease in which insulin-producing beta cells in pancreatic islets are progressively destroyed." (PMID 29415062, 2018).
type 1 diabetes (continued). "The magnitude of change in interstitial glucose with acute physical exercise in people with type 1 diabetes is dependent on the type, mode, intensity, and duration of exercise, as well as the time of day, circulating insulin levels, and whether the individual is fasted or fed." (PMID 29342932, 2018). "Type 1 diabetes mellitus (T1DM) is a chronic disease characterized by the destruction of pancreatic beta cells, inadequate insulin production, and chronic hyperglycemia." (PMID 30235836, 2018). "Importantly, our studies indicate that short-term inhibition of Y1 receptors in β-cells via pharmacological intervention may be beneficial under a condition where elevated insulin is required, such as in type 1 diabetes." (PMID 30177746, 2018). "Type 1 diabetes mellitus (T1DM) is a chronic immune-mediated disease, in which the pancreas ceases to produce enough insulin." (PMID 29696049, 2018). "Therefore, oral administration of insulin-loaded chitosan/alginate nanoparticles could be a good choice to improve the treatment of type 1 diabetes and should be investigated further in future studies." (PMID 30524677, 2018). "The vitamin D receptor (VDR) gene regulates insulin secretion from the pancreas and acts as a mediator of the immune response through vitamin D. Polymorphism in VDR causes alterations in the functioning of vitamin D, leading to type 1 diabetes (T1D) predisposition." (PMID 29333433, 2017). "Besides TNF-α-mediated mechanism in the current study, decreased osteoblastogenesis by insulin/insulin like growth factor might also suppress bone formation in the type 1 diabetes with periodontitis." (PMID 29240821, 2017). "This is supported by the frequent finding of osteopenia and osteoporosis among type 1 diabetes mellitus (T1DM) patients and supports the concept that insulin has anabolic actions on bone." (PMID 29021829, 2017). "A 54-year-old man with type 1 diabetes mellitus (T1DM) on insulin (humalog 25/35 units subcutaneous every AM/PM), albiglutide 50 mg, and canagliflozin 300 mg PO daily developed abdominal pain, nausea, and vomiting." (PMID 29978156, 2017). "Type 1 diabetes (T1D) is a chronic metabolic disorder with a complex daily treatment regime, requiring patients to carry out a variety of health-related self-care behaviors, such as monitoring blood glucose levels, administering insulin, adhering to a diet, and exercising." (PMID 28830853, 2017). "The results of this meta-analysis indicate that pramlintide supplement as an adjunct to insulin therapy might improve glycemic control and reduce body weight and insulin dose while bring transient hypoglycemia and digestive disorders in patients with type 1 diabetes." (PMID 29029531, 2017). "The present randomised controlled study investigated glucose control under open-loop and closed-loop insulin delivery, during and after unannounced afternoon moderate physical activity with or without intermittent high-intensity sprints, in young people with type 1 diabetes." (PMID 28840263, 2017). "Polymorphisms of INS have the strongest association with type 1 diabetes among non-HLA genes." (PMID 28550517, 2017). "Type 1 diabetes (T1D) is a very complex, multifactorial disorder characterized by selective autoimmune destruction of insulin-producing beta cells of the pancreas." (PMID 28701182, 2017). "Since type 1 diabetes occurs through breakdown of self-tolerance resulting in the autoimmune destruction of insulin producing β-islets of pancreas by autoreactive T lymphocytes, we hypothesized that a modulation of T cell activation would be useful to influence disease progression." (PMID 28812026, 2017). "Patients with type 1 diabetes were removed from the data by excluding patients with an age at diagnosis <35 years, or patients only treated with insulin, patients whose first therapy was insulin or patients who were prescribed insulin within 1 year of diagnosis." (PMID 29025846, 2017).
type 1 diabetes (continued). "The non-HLA genes having the strongest influence on type 1 diabetes risk are INS, PTPN22 and IL2RA." (PMID 28550517, 2017). "Moreover, the reduced insulin injection dosage could prevent the adverse effect of insulin in prolonged treatment especially in Type 1 diabetes." (PMID 29051569, 2017). "Type 1 diabetes mellitus (T1DM) results from an autoimmune attack on insulin producing beta cells that leads to immune cell infiltration of the pancreatic islets, inflammation, and beta cell death." (PMID 28717166, 2017). "Indeed, in humans, the MCT ketogenic diet has been shown to have diverse positive effects on brain function, such as increased alertness, better cognitive functioning, and improved behaviour, not only in epilepsy patients but also in patients with type 1 diabetes given an insulin infusion." (PMID 26608744, 2016). "Finally, these results contributes to revealing that dual therapy with metformin and insulin may be of interest for additional benefits for type 1 diabetes treatment." (PMID 27579154, 2016). "Type 1 diabetes mellitus (T1DM) is an organ‐specific autoimmune disorder characterized by chronic inflammation and pancreatic insulin‐producing beta cell destruction." (PMID 27241100, 2016). "Type 1 diabetes (T1D) is the second most common chronic disease of children, and yet insulin replacement is the only therapy currently approved to treat the disease." (PMID 27727279, 2016). "Future interventions might also use BEI targeting other self-care behaviors such as carbohydrate counting and insulin dosing that are challenging for teens with poorly controlled type 1 diabetes, or targeting the maintenance of an increasing percentage of blood glucose values in a healthy range." (PMID 27610391, 2016). "Type 1 diabetes (T1D) is an auto-immune disease characterized by the selective destruction of the insulin secreting beta cells in the pancreas during an inflammatory phase known as insulitis." (PMID 28082906, 2016). "The therapeutic approach for type 1 diabetes (T1D) is based on daily insulin injections, combined with blood glucose monitoring, healthy lifestyle and diet." (PMID 27400873, 2016). "Type 1 Diabetes (T1D) is an autoimmune pathology which results into selective elimination of insulin producing pancreatic β-cells owing to lymphocytic infiltration." (PMID 27575603, 2016). "In autoimmune type 1 diabetes (T1D) impaired tolerance promotes destruction of insulin-producing β-cells." (PMID 26975663, 2016). "Type 1 diabetes (T1D) is a complex trait, which develops when the insulin producing beta cells are destroyed resulting in a decreased production and secretion of insulin." (PMID 27257970, 2016). "Type 1 diabetes (T1D) results from autoimmune destruction of insulin producing β cells of the pancreatic islets." (PMID 26765526, 2016). "Type 1 diabetes mellitus (T1DM) is identified by the progressive autoimmune destruction of pancreatic beta cells, which results in a dramatic decrease of insulin production and consequent metabolic complications." (PMID 25893202, 2015). "However, diluting aspart may lead to less variable absorption and could be beneficial to young children with type 1 diabetes undergoing closed-loop insulin delivery." (PMID 25537835, 2015). "It is well recognized that the mealtime insulin requirement in type 1 diabetes (T1DM) patients is driven mostly by carbohydrate content and that monitoring it can improve glucose levels." (PMID 25767510, 2015). "Type 1 diabetes (T1D) is an autoimmune disorder characterized by the immune-mediated destruction of the insulin-producing β cells in the pancreas." (PMID 29167731, 2015). "Importantly, in some type 1 diabetes patients with severe loss of endogenous insulin secretion capacity, once-daily injection of basal insulin does not always cover the basal effect of insulin over the 24-hour period." (PMID 26435713, 2015).